RHOH (ras homolog family member H)
Diseases named in the same sentence as RHOH in open-access papers (continued):
Sharing a sentence is not in itself a finding about the gene and the disease.
B-cell neoplasm (1 paper, 2008). A group of heterogeneous lymphoid tumors generally expressing one or more B-cell antigens or representing malignant transformations of B-lymphocytes. "Conversely, it is well established that RHOH is implicated in B-cell neoplasms, however, it is currently not known whether RhoH has a role in modulation of B-cell signalling." (PMID 18823547, 2008).
Bovine mastitis (1 paper, 2023). INFLAMMATION of the UDDER in cows. "For instance, the differential expression of genes (CX3CR1, RHOH, LPAR5, and GATA3) overlapped with dMHB discriminant signatures related to SC subclinical mastitis have been found relevant to immune responses to bovine mastitis." (PMID 37373515, 2023).
Burkitt lymphoma (1 paper, 2021). A rare form of malignant mature B-cell non-Hodgkin lymphoma. "Interestingly, one of the RhoH-deficient patients also developed Burkitt lymphoma, suggesting the role of RhoH in regulating cancer development in an immunocompetent patient." (PMID 33923951, 2021).
chronic leukemia (1 paper, 2022). A slowly progressing leukemia characterized by a clonal (malignant) proliferation of maturing and mature myeloid cells or mature lymphocytes. "RHOH, a member of the RhoE/Rnd3 subfamily of GTPases, is highly expressed in B cells, suggesting that it is involved in the development of B-cell malignant leukemia and is closely related to the immune microenvironment in chronic leukemia." (PMID 35432443, 2022).
chronic obstructive pulmonary disease (1 paper, 2008). A chronic and progressive lung disorder characterized by the loss of elasticity of the bronchial tree and the air sacs, destruction of the air sacs wall, thickening of the bronchial wall, and mucous accumulation in the bronchial tree. "In an early study it was shown that stimulation of neutrophils with GM-CSF leads to an upregulation of RhoH mRNA, suggesting that RhoH may play a role in diseases characterised by neutrophilic inflammation such as chronic obstructive pulmonary disease (COPD)." (PMID 18823547, 2008).
dermatitis (1 paper, 2021). An inflammatory process affecting the skin. "Although the number of peripheral mature T cell decreases in RhoH-null mice, the number of TH17 cells was shown to increase in the RhoH−/− mice with dermatitis symptoms, causing an increase in IL−22, IL−23 and IL−17 production." (PMID 33923951, 2021).
epidermodysplasia verruciformis (1 paper, 2021). A rare inherited genodermatosis characterized by chronic infection with human papillomavirus (HPV) leading to polymorphous cutaneous lesions and high risk of developing non melanoma skin cancer. "Among the 400 mutated genes identified in PIDs, RhoH has been found in two patients with PID, particularly in patients with epidermodysplasia verruciformis (EV)." (PMID 33923951, 2021).
Graves disease (1 paper, 2014). Graves' disease is an autoimmune disorder that leads to overactivity of the thyroid gland (hyperthyroidism).It is caused by an abnormal immune system response that causes the thyroid gland to produce too much thyroid hormones. "RHOH/CHRNA9 rs6832151, previously associated with Grave's Disease, generalized to serum TSH levels in African Americans (p = 0.01, β = −0.10)." (PMID 25436638, 2014).
lupus (1 paper, 2021). "Thus, the involvement of RhoH-induced IFN-γ production and subsequently BAFF production may underpin lupus malignancy that probably occurs through the modulation of NF-κB activation." (PMID 33923951, 2021).
lymphopenia (1 paper, 2019). Reduction in the number of lymphocytes. "Disseminated warts have also been frequently found in several autosomal recessive genetic defects that present with CD4 lymphopenia (e.g., RAG1, RHOH, MST1, CORO1A, DOCK8)." (PMID 31781092, 2019).
metastatic melanoma (1 paper, 2023). A melanoma that has spread from its primary site to another anatomic site. "In a study on the screening of markers for early diagnosis of metastatic melanoma, RHOH was identified as central gene involved in immune response and tumor cell progression." (PMID 36710485, 2023).
peritonitis (1 paper, 2022). Inflammation of the peritoneum (tissue that lines the abdominal wall and covers most of the organs in the abdomen). "In order to verify the regulatory role of RhoH in vivo, we used an acute murine peritonitis model in which a low intraperitoneal dose of GFP-E. coli is applied." (PMID 36108062, 2022). "In addition, the regulatory role of RhoH was further evaluated in an E. coli-induced peritonitis model." (PMID 36108062, 2022).
psoriasis (1 paper, 2021). An autoimmune condition characterized by red, well-delineated plaques with silvery scales that are usually on the extensor surfaces and scalp. "Taken together, RhoH and its interacting partners may serve as valuable targets for the effective treatment of autoimmune-related diseases, including PIDs, psoriasis and SLE." (PMID 33923951, 2021). "The role of RhoH in psoriasis might be due to its ability to regulate T cell development as deregulation of T cell causes aberrant production of psoriatic cytokines IL−17, IFN-γ, TNF, and IL−22." (PMID 33923951, 2021). "Besides involved in PIDs, lack of RhoH was also shown to induce psoriasis-like chromatic dermatitis by stimulating T cell differentiation into TH17 cells." (PMID 33923951, 2021).
WHIM syndrome (1 paper, 2023). "HPV‐related papilloma cancer is seen in WHIM syndrome or EVER1, EVER2, MST1, RHOH, MAGT1, ITK deficiencies." (PMID 37102642, 2023).
tumor (49 papers, 2012 to 2026). "Two tumor samples, T14 and T19, displayed a loss of 4p13 that encodes RHOH, a member of the RAS superfamily, and PHOX2B, a homeobox transcription factor." (PMID 34285259, 2021). "Our data revealed the critical roles of miR-22 in inhibiting Rho, RAC1, RhoG, and RhoH GTPase cycles at the tumor margin or outside the tumors." (PMID 39953622, 2025). "The mRNA expression level of RHOH was related to age (p = 0.023) and the tumor stage (p = 0.027) of LUAD patients." (PMID 36710485, 2023). "RHOH therefore acts as a crucial point in the regulatory pathways of immunoreactions and is a promising target for increasing the effectiveness of anti-tumor immune therapy." (PMID 31672930, 2019). "In addition, the expression of RHOH was related to age and tumor stage; larger‐sample studies are required to verify our findings and conclusions." (PMID 36710485, 2023). "In addition, RHOH has been revealed to regulate the tumor microenvironment." (PMID 36710485, 2023). "Interestingly, RhoH is widely known as a tumour suppressor, suggesting that deregulation of RhoH activity may influence cancer progression." (PMID 33923951, 2021). "CD44, ETS2, RHOH, and TRIB1 also affect the proliferation and invasion ability of tumor cells by regulating the expression of downstream genes." (PMID 39684426, 2024).
cancer (16 papers, 2008 to 2025). A tumor composed of atypical neoplastic, often pleomorphic cells that invade other tissues. "As such, RhoH and its associated proteins are potential attack points, especially in the treatment of cancer and immune-related diseases." (PMID 33923951, 2021). "However, mutations within Rho GTPases, except for RhoH, were believed to be rare in cancer until recently." (PMID 27104658, 2016). "However, indolent forms of a certain cancer often have lower mutation frequencies for RHOH than more aggressive forms." (PMID 18823547, 2008). "While other small Rho GTPases promote cell division and inflammatory response via NF-κB signalling, RhoH negatively regulates cancer-related signalling by inhibiting IκB degradation." (PMID 33923951, 2021). "As such, the role of RhoH as a modulator of signalling cascades should be further elucidated to understand its biological implications in patients with cancer." (PMID 33923951, 2021). "RhoH protein expression is significantly correlated with the aggressiveness of the malignancies and potentially involved in promoting cancer development among immune-deregulated patients." (PMID 33923951, 2021). "Despite several studies that correlate the low protein levels of RhoH with cancer progression, increased RhoH protein expression was also found to contribute to malignancy." (PMID 33923951, 2021). "Based on this analysis, we tested for RhoH expression in a selection of cancer cell lines, including those with high and low expression based on our CCLE analysis." (PMID 29510700, 2018). "It was recently shown that reduced RhoH levels can be connected to cancer and protection from apoptosis." (PMID 20738848, 2010). "In comparison to the number of studies on the putative role of RhoH in cancer, only a very limited number of publications deal with the function of RhoH as a signalling molecule." (PMID 18823547, 2008). "It will therefore be of crucial importance to gain a better understanding of RhoH as a modulator of signalling cascades in order to better understand its biological implications in cancer patients." (PMID 18823547, 2008). "In addition, established cancer genes like Lmo2, RhoH, Trim33, Mll, and Hspca are candidate target genes of less frequently mutated CISs, indicating that lower ranked CISs (carrying 4–5 insertions) may represent bona fide cancer genes." (PMID 18485879, 2008). "Overall, deregulation of RhoH protein expression can modulate the activity of several proteins, including the other small Rho GTPases, which are known to be significantly involved in cell survival and proliferation, thus promoting cancer progression." (PMID 33923951, 2021). "The exact mechanism for this cancer development is still not well understood, but it might be due to the ability of RhoH to regulate the activities of other cancer-related small Rho GTPases, including RhoA, Cdc42, Rac1 and RhoF." (PMID 33923951, 2021). "Unexpectedly, we identified RhoH as a key regulator of cancer cell migration." (PMID 29510700, 2018). "Two recent publications now link low RhoH protein levels to cancer." (PMID 20738848, 2010). "Thus, low levels of RhoH resulting from aSHM might directly or indirectly promote Rac1-, RhoA- or Cdc42-induced cell division and migration, leading to an increase in cancer progression." (PMID 33923951, 2021). "This implies that PAK2 could act with RhoH to promote cancer progression." (PMID 29510700, 2018). "Interestingly, many of the DMGs identified had multiple roles and several were potential cancer biomarkers or were previously shown to be implicated in various types of cancers, including ABLIM1, ADAM12, ARHGEF4, FBLN2, ITGA6, LRPAP1, Ly9, NT5E, PITPNC1, PLCG1, OBSCN, RHOH, SPTBN1, SPOCK2 and SPRY1." (PMID 41159936, 2025). "In a first attempt at understanding the signalling of RhoH in cancer cells, or rather its absence of signalling, it was shown that expression of RhoH is necessary to prevent Rac1 mediated protection from drug-induced apoptosis." (PMID 18823547, 2008).
cancer (continued). "Most data gathered so far however indicate that in human cancers the absence of a functional RhoH protein or reduced RhoH expression levels rather than its overexpression may play a role in pathogenesis." (PMID 18823547, 2008).
hematological disease (2 papers, 2019 to 2023). "Abnormal expression of RHOH usually occurs in hematological disease, but it is rarely reported in solid tumors." (PMID 36710485, 2023).
RHOH also shares sentences with these, for which no sentence is quoted: lung adenocarcinoma (4 papers); adenocarcinoma (2); Hodgkins lymphoma (2); myeloproliferative disorder (2); neuroblastoma (2); small cell lung carcinoma (2); AIDS (1); ataxia telangiectasia (1); autoimmune disease (1); Brain Tumour (1); cardiac hypertrophy (1); Clouston syndrome (1); colitis (1); colon adenocarcinoma (1); colorectal tumor (1); coronary artery disease (1); COVID-19 (1); Ewing sarcoma (1); fibrosarcoma (1); heart failure (1); hypertrophic obstructive cardiomyopathy (1); infarction (1); infection (1); lung NET (1); metastatic tumors (1); mucinous adenocarcinoma (1); myeloproliferative neoplasm (1); Netherton syndrome (1); neutrophilic diseases (1); peripheral arterial disease (1).
A further 5 diseases each share a sentence with RHOH in 1 paper.